CD24 (CD24 molecule)
Diseases named in the same sentence as CD24 in open-access papers (continued):
Sharing a sentence is not in itself a finding about the gene and the disease.
tumor (continued). "In TNBC, a novel engineered nanoparticle (P-ACD24/CEL + P/shMFN1) synergistically elicits an anti-tumor immune response by blocking CD24, inducing tumor cell apoptosis, and reversing the M2-TAMs phenotype, thereby achieving the effect of combined immunotherapy." (PMID 40223929, 2025). "Additionally, another miRNA—hsa-miR-34a—acts as a tumor suppressor, post-transcriptionally downregulating CD24 and SRC, which consequently decreases hsa-miR-21-5p expression and increases the expression of PDCD4 and PTEN." (PMID 40362695, 2025). "We also observed that the tumor-suppressive efficacy of nanomaterials encapsulated in unmodified EM was inferior to that of those delivered via anti-CD24-modified EM, underscoring the necessity of targeted surface modification to enhance therapeutic performance." (PMID 41281650, 2025). "Furthermore, the tumor-suppressive properties of miR-10a-5p and its regulatory effects on CD24 and TFR1 expression highlight potential therapeutic avenues." (PMID 41551164, 2025). "Likewise, although combining 015s with the CD24-targeted ADC cG7-MMAE improved tumour control, a formal demonstration of synergy will require inclusion of the corresponding monotherapy arms; these controls will be incorporated into subsequent studies." (PMID 40806691, 2025). "Additionally, the relationship between CD24 and side effects of tumor treatment is also under clinical trial investigation." (PMID 40486886, 2025). "However, our prior work showed that CD24 is essential for tumor growth and metastatic progression in human TNBC cells, as it promotes oncogenic signaling via EGFR and MET." (PMID 40783744, 2025). "Furthermore, CD24 knockdown in tumor cells markedly suppressed the expression of the senescence marker P21 compared with control cells." (PMID 40777020, 2025). "Additionally, in vivo and in vitro experiments need to be conducted to further explore the molecular function of the MUCL1(+) CD24(+) tumor cluster." (PMID 41142825, 2025). "Given the established role of somatic mutations in modulating cellular infiltration patterns, we propose that tumor-derived genetic alterations may similarly regulate MUCL1(+) CD24(+) cell expression within the tumor microenvironment." (PMID 41142825, 2025). "Interestingly, combining the status of CD24 expression in tumor cells with the density of CD3+ tumor-infiltrating lymphocytes (TIL), a microenvironment/immune-related marker, identified a high-risk subgroup with the worst DFS and OS." (PMID 40647395, 2025). "In addition to directly acting on tumor cells, CD24 can also interact with Siglec-10 to regulate the physiological functions of immune cells and affect the immune response to tumors." (PMID 40486886, 2025). "In this tumour (Mel110), 13% of the total malignant cell population was CD24+CD271+." (PMID 40754577, 2025). "Notably, CD24-targeted vesicles demonstrated superior tumor suppression compared to non-targeted formulations, which can be attributed to enhanced tumor accumulation mediated by CD24 antibody-directed targeting." (PMID 41281650, 2025). "This transformation is significant as it suggests that targeting CD24 could enhance anti-tumor immune responses and improve the efficacy of immunotherapies." (PMID 40783744, 2025). "CD24 is another novel “don’t eat me” protein highly expressed in some tumor types." (PMID 40380196, 2025). "Emerging evidence highlights the CD24–Siglec-10 axis as a critical innate immune checkpoint; the engagement of Siglec-10 on macrophages by CD24 transduces a potent anti-phagocytic signal, thereby shielding tumor cells from clearance, particularly in PD-L1-negative TNBC phenotypes." (PMID 41516322, 2025). "Moreover, CD24 is found to be overproduced in pathologically stem cells (CSCs), highly specific cells within tumors with the ability to self-renew and initiate tumor growth." (PMID 40297849, 2025). "CD24 serves as a critical “don’t eat me” signal molecule expressed by tumor cells." (PMID 40873588, 2025).
tumor (continued). "It is recently reported that CD24 expressed on tumor cells can exert a “don’t eat me” signal when binding to Siglec-10 on macrophages, which could impede macrophage phagocytosis activity." (PMID 40779581, 2025). "Interestingly, CD24-Fc ameliorates irAEs when used in combination with immune checkpoint inhibitors in tumor immunotherapy in humanized NSG mice engrafted with human hematopoietic stem cells." (PMID 40779581, 2025). "Collectively, these observations suggest that CT features reflecting tumor aggressiveness may serve as imaging surrogates of miR-10a-5p/TFR1/STAT3/CD24 dysregulation." (PMID 41551164, 2025). "Foundational xenograft work identified a CD44+/CD24+/ESA+ CSC subpopulation with robust tumor-initiating capacity and self-renewal; as few as ~100 cells formed tumors and showed elevated Sonic Hedgehog expression, establishing CSC linkage to developmental signaling and tumor initiation in vivo." (PMID 40868290, 2025). "In patients with cervical squamous cell carcinoma who received postoperative radiotherapy, patients with a high percentage of CD24+ tumor cells were found to have significantly lower distant metastasis-free survival and overall survival than patients with a high percentage of CD24− cells." (PMID 40486886, 2025). "Importantly, targeting DYRK1B downregulated the “don’t eat me” signal CD24 on cancer cells, resulting in enhanced tumor cell phagocytosis by macrophages." (PMID 39863750, 2025). "Additionally, CD24 acts as a “don’t eat me” signal, blocking the ability of immune system to recognize and destroy cancer cells, thereby facilitating tumor growth and spread." (PMID 38881902, 2024). "CD24 has been shown to suppress the activity of natural killer cells and dendritic cells, which are important components of the immune system that play a critical role in tumor surveillance and elimination." (PMID 38881902, 2024). "Therefore, it is necessary to further explore the molecular regulatory mechanisms of CD24, particularly in the tumour microenvironment (TME), the local biological environment of solid tumours." (PMID 38702326, 2024). "Additionally, CD24 has been studied extensively in the context of cancer, where it has been found to play a role in tumor growth, invasion, and metastasis." (PMID 38881902, 2024). "The roles of cytoplasmic CD24 in tumor growth and metastasis are not fully understood." (PMID 38279998, 2024). "In addition, qRT-PCR of the resected vehicle-treated tumors confirmed that CD24 expression in the tumor models was comparable to that observed previously between in vitro and in vivo tumors in this study." (PMID 38214542, 2024). "Interestingly, CD24 was identified as a surface marker for the tumor-initiating cells in MM as well." (PMID 38339250, 2024). "And CD24 is one of the markers expressed by tumor stem cells." (PMID 39050844, 2024). "Moreover, 94% (15/16), showed high expression of PDGFRβ, 88% (14/16) exhibited the presence of PDGFRa, and 81% (13/16) showed similar expression in the tumor stroma, while high CD24 expression in the tumor was observed in 63% of cases (10/16)." (PMID 38791897, 2024). "Notably, CD24 binds to P-selectin on platelets and endothelial cells, facilitating tumor cell migration and metastasis." (PMID 38881902, 2024). "This synergy between the Hippo-YAP pathway and CD24 not only underscores the complexity of tumor-immune interactions but also opens new avenues for therapeutic interventions aimed at disrupting these oncogenic signaling cascades to restore immune system competency in targeting malignancies." (PMID 38881902, 2024). "However, antibody-based blockade of CD24 or Siglec-10 enhance cancer cell engulfment by macrophages, reducing tumor growth." (PMID 40836974, 2024). "In the APCMin/+ mouse model of colorectal carcinogenesis, CD24 knock-out reduces tumour development in a dose-dependent way (reduction in burden with heterozygous loss and no tumour production with homozygous knock-out)." (PMID 38505585, 2024).
tumor (continued). "CD24 was found to be highly expressed in tumor tissues, contributing to immune evasion." (PMID 39596658, 2024). "The exploration of CD24 as a phagocytosis checkpoint opens new avenues for cancer immunotherapy, offering insights into the intricate balance between immune activation and suppression within the tumor microenvironment." (PMID 38881902, 2024). "To understand the impact of CD24 on patient prognosis, we analyzed the clinical correlation between CD24 expression levels and various cancer types based on key clinical factors, including age, tumor stage, and tumor purity." (PMID 39791710, 2024). "The experimental results showed that CD24 knockdown effectively inhibited the occurrence of tumor in vivo, which was reflected in the significantly lighter weight and smaller volume of subcutaneous heterografts in nude mice in CD24 knockdown group compared with the control group." (PMID 38914670, 2024). "Furthermore, the expression of CD24 and its role as a phagocytosis checkpoint varies across different tumor types and stages, suggesting a need for targeted approaches in utilizing this axis for cancer therapy." (PMID 38881902, 2024). "Together, these data suggest that CD24 may promote an immunomodulatory role in the tumor, presenting a possible explanation for the profound differences observed between tumor and host outcomes in vivo." (PMID 38214542, 2024). "Notably, PAC-SABIs demonstrated a significant reduction in tumor growth in both BC and PC models, surpassing the efficacy of anti-CD24 mAb or SAMIs." (PMID 38971872, 2024). "Consequently, CD24 not only enhances our comprehension of tumor biology mechanisms, but also emerges as a potential tumor marker and a novel target for therapeutic interventions." (PMID 39184916, 2024). "The results suggest that nanosphere-antiCD24 may be used in tumor therapy to disrupt the CD24/Siglec-10 signaling pathway and degrade membrane proteins." (PMID 38279998, 2024). "Recent reports have suggested an immunosuppressive role for CD24 in tumor cells." (PMID 38214542, 2024). "CD24-Fc binding to Siglec-10 on macrophages might activate a “don’t eat me” signal, a mechanism recently observed in tumor cells involving CD24, which could impede macrophage activity." (PMID 39763958, 2024). "Blocking CD24-Siglec interactions may enhance anti-tumor immune responses, similar to strategies targeting CD47 or PD-L1/PD-1." (PMID 39040441, 2024). "Mechanistically, sialoglycan ligands, such as CD24 on tumor cells, activate the Siglec‐G‐SHP2 axis in CD8+ T cells, impairing metabolic reprogramming from oxidative phosphorylation to glycolysis, which dampens cytotoxic T lymphocyte (CTL) activation, expansion, and cytotoxicity." (PMID 39373395, 2024). "Therefore, since CD24-Siglec-10 is an innate immune checkpoint essential for mediating anti-tumor immunity, it has become a very promising therapeutic target for tumor immunotherapy." (PMID 38725856, 2024). "Therefore, CAR-T cells targeting CD24 are designed to recognize minimal residual MM cells and block the CD24-Siglec-10 pathway inducing tumor cell clearance by phagocytic macrophages." (PMID 39234257, 2024). "CD24/Siglec-10 binding has also associated with autoimmune disorders, GVHD, and tumor progression." (PMID 38279998, 2024). "The expression level of CD24 in subcutaneous tumor tissues was further detected by WB experiment, and the results showed that the expression level of CD24 in subcutaneous tumor tissues of the control group was significantly higher than that of the experimental group." (PMID 38914670, 2024). "The interaction of CD24-Siglec-10 is a ‘don’t eat me’ signal for tumor cells." (PMID 38339250, 2024). "In immunology, as a primarily costimulatory molecule, CD24 can achieve effective immunosuppression and tumor immune escape via activating a series of intracellular signal pathways and regulating multiple immune cells, for instance, T cells, B cells, macrophages, and NK cells." (PMID 37875600, 2023).
tumor (continued). "The role of CD24 is highlighted by the overexpression on different tumors, and knock-down of CD24 expression revealed its function in tumor cells: CD24 depletion reduced cell proliferation, enhanced sensitivity to undergo apoptosis, and modulated STAT3-mediated gene expression." (PMID 37626918, 2023). "The tumor tissue was digested into single cells and labeled with CD24 and CD44 antibodies." (PMID 36707875, 2023). "Therefore, the observed EpCAM+Vim+CD24+ cells in our tumour specimens are highly likely to be a tumour cell population." (PMID 37975646, 2023). "CD24 modulates the immune response to multiple tumor types by interacting with Siglec-10." (PMID 37894750, 2023). "CD24 is a mucin-like glycosylated glycophosphatidylinositol-anchored molecule, which could help resist anoikis in various tumours (Li, Sun & Wang, 2015)." (PMID 37842046, 2023). "Some study also reported that with the help of anti-CD24 antibody, the chemotherapy could exert more advantage when targeting chemotherapy-resistant tumor stem cells." (PMID 37359556, 2023). "On the other hand, using CD24-Fc later with booster vaccination would avoid the initial suppressive effect, thus allowing the vaccine to activate immune pathways and boost immune cell infiltrates in the tumor." (PMID 37346042, 2023). "CD24 is expressed not only in tumor cells but also in immune cells." (PMID 36882451, 2023). "More recently, emerging data indicate that CD24 have an intriguing role in tumor evasion from phagocytosis, hypothesized to act as a “don’t eat me signal”." (PMID 37919766, 2023). "We next stratified 24 human primary OSCC specimens into 12 tumours that had evidence of lymph node metastasis or perineural spread, and 12 that remained metastasis free, and stained them for EpCAM, Vimentin and CD24." (PMID 37975646, 2023). "Imaging the tumour body and adjacent stroma in sections of human OSCC specimens, we detected single cells co-expressing EpCAM, Vimentin and CD24 in the stromal region surrounding the tumour, confirming that these cells can be detected in human tumour specimens." (PMID 37975646, 2023). "In addition, inhibition of CD24 inhibited tumor growth, which was also the case for treatments targeting mTOR and the PI3K/Akt pathway and STAT3." (PMID 37919766, 2023). "Furthermore, numerous anti-CD24 mabs have been selected in combination with PD-1 for a significant anti-tumor effect." (PMID 37484024, 2023). "The current study evaluates whether CD24-Fc could be used to prevent or treat irAE while evaluating the effect on T cell anti-tumor immunity with tumor vaccine therapy." (PMID 37346042, 2023). "To address if the reduced self-renewal capacity of MCF7 NELF-E KO cells may be due to a loss of cancer stem cells (CSCs) or tumor-initiating cells (TICs), we performed flow cytometry analysis using CD44 and CD24 surface markers." (PMID 37117180, 2023). "The functions of cytoplasmic CD24 in tumor proliferation and metastasis are controversial." (PMID 36882399, 2023). "Besides, aggressive tumor‐activated bone marrow cells can upregulate CD24 expression on indolent tumor cells and enhance the infiltration of VEGFR2+ tumor‐associated endothelial cells." (PMID 37719444, 2023). "Moreover, the difference in tumor growth between CD24−/− and CD24+/− mice was blunted by immunodepleting of MDSCs." (PMID 38138858, 2023). "We demonstrated that GCEPs have self-renewal capacity, tumor formation capacity, and differentiation potential in vitro, thereby producing cells with different surface markers derived from single cells with the CD24+CD44+CD54+EpCAM+ phenotype." (PMID 36737794, 2023). "In recent years, CD24 gene has raised interest predicting tumor behavior and treatment response." (PMID 38138858, 2023). "CD24 has been identified as a significant marker for tumour diagnosis and prognosis." (PMID 38137380, 2023).
tumor (continued). "Siglec-10 binds tightly to CD24 in a sialic acid-dependent manner, leading to the inhibition of macrophage signaling cascades and diminished efficiency of phagocytosis, ultimately enhancing tumor immune escape." (PMID 38313430, 2023). "Moreover, increased phosphorylation of STAT3 and expression of STAT3 target genes, NANOG and C-MYC in CD24+ OCSC, when inhibited with JAK2, induces cytotoxicity in CD24+ cells, reduces tumor metastasis, and prolongs overall survival." (PMID 37445860, 2023). "The CD24-expressing tumor cells could identify and combine the P-selectin on platelets, leading to tumor cells excrete and subsequently metastasis." (PMID 37359556, 2023). "Additionally, Rg7S-MICA successfully attracted NK cells and stimulated the release of cytokines in CD24+ HCC-bearing nude mice to produce superior anti-tumor activity." (PMID 37846296, 2023). "CD24 on the surface of tumor cells could interact with Siglec-10 on the surface of immune cells, to mediate the immune escape of tumor cells." (PMID 37359556, 2023). "CD24 and CD200 are overexpressed across diverse cancer types and serve as signaling checkpoints by engaging their respective receptors, Siglec-10 and CD200 receptor, which are expressed on tumor-associated myeloid cells." (PMID 37894750, 2023). "In particular, CD24 is less common in tumor tissues than in normal tissues." (PMID 37907864, 2023). "Partially restoring the phagocytic ability of macrophages towards tumour cells could be achieved by controlling the breakdown of CD24 protein." (PMID 37784253, 2023). "It is noteworthy that the data could be replicated with other membrane proteins, confirming the impact of CD24 protein degradation in altering tumor immunosuppression." (PMID 36866919, 2023). "Meanwhile, CD24-Siglec10, as a congenital immune checkpoint, could also regulate macrophage-mediated anti-tumor immune responses for drug development." (PMID 37484024, 2023). "The methods by which CD24 supports tumour progression via Src are explained as follows." (PMID 38137380, 2023). "Moreover, the dAbPD−L1/CD24-mPDA@CuO2 NRs exhibit targeted chemodynamic therapy (CDT) with the ability to self-supply H2O2 within the tumor microenvironment, leading to efficient suppression of 4T1 breast tumors." (PMID 37875918, 2023). "Blockade of CD24 and its receptor Siglec-10 reduces tumor growth and extends patient survival." (PMID 37346042, 2023). "Enrichment of EpCAM+Vim+CD24+ cells in the stroma surrounding metastatic tumours." (PMID 37975646, 2023). "The lncRNA-H19 could reduce the expression of cell-surface CD24 in tumor cells and regulate the tumor immune escape." (PMID 37359556, 2023). "However, we did not detect any unique characteristic of patients with a high percentage of CD24+/CD11b− among PBLs, or correlation to tumor characteristics, apart from male gender." (PMID 38138858, 2023). "CD24 plays a pivotal role in promoting tumor growth, metastasis, and immune evasion." (PMID 38313430, 2023). "Studies have shown that CD24 is highly expressed in various tumor cells." (PMID 38313430, 2023). "Therefore, targeting CD24 is meaningful in treating various tumours with high CD24 expression and poor prognosis." (PMID 38137380, 2023). "Another molecule that is frequently overexpressed by diverse tumor types is CD24." (PMID 38033495, 2023). "Furthermore, the specific binding of purified SIRPα-Fc and Siglec10-Fc to CD47 or CD24, respectively, enhanced macrophage‐mediated tumor cell phagocytosis in vitro." (PMID 38016957, 2023). "NANOG was highly expressed in the miR-135b-5p-high group within clusters 1 and 14, and elevated expression of C-MYC and CD24 was observed in the miR-135b-5p-high group within cluster 14, indicating a more remarkable stemness property of tumor cells in HCC with high miR-135b-5p expression." (PMID 36755690, 2023). "Additionally, SWA-11 interferes with CD24 signaling and regulates the tumor microenvironment, which sensitizes tumor cells to gemcitabine chemotherapy." (PMID 37484024, 2023).